ITCH (itchy E3 ubiquitin protein ligase)
Description:
Acts as an Acts as an E3 ubiquitin-protein ligase which accepts ubiquitin from an E2 ubiquitin-conjugating enzyme in the form of a thioester and then directly transfers the ubiquitin to targeted substrates. Catalyzes 'Lys-29'-, 'Lys-48'- and 'Lys-63'-linked ubiquitin conjugation. Involved in the control of inflammatory signaling pathways. Essential component of a ubiquitin-editing protein complex, comprising also TNFAIP3, TAX1BP1 and RNF11, that ensures the transient nature of inflammatory signaling pathways. Promotes the association of the complex after TNF stimulation. Once the complex is formed, TNFAIP3 deubiquitinates 'Lys-63' polyubiquitin chains on RIPK1 and catalyzes the formation of 'Lys-48'-polyubiquitin chains. This leads to RIPK1 proteasomal degradation and consequently termination of the TNF- or LPS-mediated activation of NFKB1. Ubiquitinates RIPK2 by 'Lys-63'-linked conjugation and influences NOD2-dependent signal transduction pathways. Regulates the transcriptional activity of several transcription factors, and probably plays an important role in the regulation of immune response. Ubiquitinates NFE2 by 'Lys-63' linkages and is implicated in the control of the development of hematopoietic lineages. Mediates JUN ubiquitination and degradation (By similarity). Mediates JUNB ubiquitination and degradation. Critical regulator of type 2 helper T (Th2) cell cytokine production by inducing JUNB ubiquitination and degradation (By similarity). Involved in the negative regulation of MAVS-dependent cellular antiviral responses. Ubiquitinates MAVS through 'Lys-48'-linked conjugation resulting in MAVS proteasomal degradation. Following ligand stimulation, regulates sorting of Wnt receptor FZD4 to the degradative endocytic pathway probably by modulating PI42KA activity. Ubiquitinates PI4K2A and negatively regulates its catalytic activity. Ubiquitinates chemokine receptor CXCR4 and regulates sorting of CXCR4 to the degradative endocytic pathway following ligand stimulation by ubiquitinating endosomal sorting complex required for transport ESCRT-0 components HGS and STAM. Targets DTX1 for lysosomal degradation and controls NOTCH1 degradation, in the absence of ligand, through 'Lys-29'-linked polyubiquitination. Ubiquitinates SNX9. Ubiquitinates MAP3K7 through 'Lys-48'-linked conjugation (By similarity). Together with UBR5, involved in the regulation of apoptosis and reactive oxygen species levels through the ubiquitination and proteasomal degradation of TXNIP: catalyzes 'Lys-48'-/'Lys-63'-branched ubiquitination of TXNIP. ITCH synthesizes 'Lys-63'-linked chains, while UBR5 is branching multiple 'Lys-48'-linked chains of substrate initially modified. Mediates the antiapoptotic activity of epidermal growth factor through the ubiquitination and proteasomal degradation of p15 BID. Ubiquitinates BRAT1 and this ubiquitination is enhanced in the presence of NDFIP1. Inhibits the replication of influenza A virus (IAV) via ubiquitination of IAV matrix protein 1 (M1) through 'Lys-48'-linked conjugation resulting in M1 proteasomal degradation. Ubiquitinates NEDD9/HEF1, resulting in proteasomal degradation of NEDD9/HEF1.
Synonyms: AIP4; NAPP1; ADMFD; AIF4
Tractability: Small molecule: it has a high-quality binding pocket. Antibody: UniProt places it where antibodies can reach, with high confidence; its Gene Ontology location is reachable by antibodies, with high confidence. PROTAC: UniProt records ubiquitination sites on it; ubiquitination databases record sites on it; its protein half-life has been measured.
Target class: Enzyme; Transferase
Gene: Protein-coding gene on chromosome 20 (34,363,235 to 34,511,773, forward strand). Ensembl gene ENSG00000078747.
Subcellular location: Cell membrane; Cytoplasm; Nucleus; Early endosome membrane; Endosome membrane
Subcellular location (Human Protein Atlas): Nucleoplasm; Vesicles
Pathways (Reactome):
Signal Transduction: Activated NOTCH1 Transmits Signal to the Nucleus; Degradation of GLI1 by the proteasome; Downregulation of ERBB4 signaling; Hedgehog 'on' state
Immune System: Antigen processing: Ubiquitination & Proteasome degradation; NOD1/2 Signaling Pathway; Negative regulators of DDX58/IFIH1 signaling
Disease: SARS-CoV-1 activates/modulates innate immune responses
Gene expression (Transcription): RUNX1 regulates transcription of genes involved in differentiation of HSCs
Programmed Cell Death: Regulation of necroptotic cell death
Gene Ontology:
Molecular function: arrestin family protein binding; CXCR chemokine receptor binding; protein binding; ribonucleoprotein complex binding; ubiquitin protein ligase activity; ubiquitin-like protein ligase binding; ubiquitin-protein transferase activity; ubiquitin-ubiquitin ligase activity; ubiquitin-like protein transferase activity; ligase activity
Biological process: negative regulation of apoptotic process; negative regulation of cytoplasmic pattern recognition receptor signaling pathway; negative regulation of defense response to virus; positive regulation of receptor catabolic process; proteasome-mediated ubiquitin-dependent protein catabolic process; protein autoubiquitination; protein branched polyubiquitination; protein K29-linked ubiquitination; protein K48-linked ubiquitination; protein K63-linked ubiquitination; protein monoubiquitination; protein ubiquitination; receptor internalization; ubiquitin-dependent protein catabolic process; inflammatory response; negative regulation of canonical NF-kappaB signal transduction; negative regulation of JNK cascade; negative regulation of type I interferon production; nucleotide-binding domain, leucine rich repeat containing receptor signaling pathway; regulation of cell growth; regulation of hematopoietic stem cell differentiation; regulation of necroptotic process; regulation of protein deubiquitination; symbiont entry into host cell; negative regulation of immune system process; and 4 more
Cellular component: cytoplasm; cytoplasmic vesicle; early endosome; early endosome membrane; endosome membrane; extracellular exosome; membrane; nucleoplasm; nucleus; plasma membrane; protein-containing complex; cytosol; mitochondrion; cell cortex; cell periphery
Genetic constraint (gnomAD): Loss-of-function variants: 19 observed, 81.27 expected, observed/expected ratio (o/e) 0.23, 90% interval 0.16 to 0.34. The upper end of that interval is the gene's LOEUF score, 0.34, which puts it in group 1 of 6, group 1 being the genes least tolerant of losing a copy. Missense variants: 481 observed, 823.73 expected, observed/expected ratio (o/e) 0.58, 90% interval 0.54 to 0.63. Synonymous variants: 261 observed, 278.79 expected, observed/expected ratio (o/e) 0.94, 90% interval 0.85 to 1.04.
Gene-disease validity (ClinGen):
ClinGen rates the evidence that ITCH causes each of these diseases.
syndromic multisystem autoimmune disease due to ITCH deficiency (autosomal recessive): Definitive.
Homologues: Orthologues: chimpanzee ITCH (100% identical), macaque ITCH (99% identical), guinea pig ITCH (98% identical), rabbit ITCH (98% identical), dog ITCH (97% identical), mouse Itch (96% identical), rat Itch (95% identical), pig ITCH (94% identical), tropical clawed frog itch (79% identical), zebrafish itcha (75% identical), zebrafish itchb (73% identical). Paralogues in human: WWP1 (62% identical), WWP2 (57% identical), NEDD4L (36% identical), SMURF2 (35% identical), HUWE1 (35% identical), SMURF1 (34% identical), NEDD4 (34% identical), HECW1 (34% identical), HECW2 (34% identical), HACE1 (26% identical), TRIP12 (23% identical), HECTD4 (22% identical), and 12 more.
Diseases named in the same sentence as ITCH in open-access papers:
ITCH is named in the same sentence as 100 diseases in open-access papers, as found by Europe PMC text mining. Sharing a sentence is not in itself a finding about the gene and the disease. The quoted sentences say what the papers report.
lung carcinoma (35 papers, 2016 to 2026). "Simultaneously, we further evaluated the association between cir-ITCH expression in lung cancer tissues and clinical characteristics of lung cancer patients." (PMID 27642589, 2016). "When treated under hypoxic conditions, ITCH expression was downregulated in lung cancer (LC) cell lines, which resulted in increased migration and invasion abilities of LC cells." (PMID 37760946, 2023). "In lung cancer the down-regulation of circ-ITCH brings to an increase of miR-7 and miR-214, thereby to a decrease of their target gene, ITCH." (PMID 33976116, 2021). "Circ-ITCH plays an inhibitory role in lung cancer progression by sponging miR-7 and miR-214 and regulating the expression of ITCH59,60." (PMID 33976116, 2021). "Circ-ITCH also acts as a tumor suppressor in breast cancer through sponging miR-224 and miR-17, or in lung cancer through sponging miR-224 and miR-7 and in esophageal cancer through sponging miR-17 miR-7, and miR-21421–23." (PMID 34531437, 2021). "Circ-ITCH downregulation was reported in esophageal squamous cell cancer, colorectal cancer, lung carcinoma as well as hepatocellular carcinoma by sponging ITCH targeting miRNAs20–22." (PMID 34531437, 2021). "In lung cancer samples from patients, ITCH expression was found to be significantly upregulated, and depletion of ITCH inhibited cell proliferation and induced apoptosis in the lung cancer cells via the mitochondrial pathway." (PMID 31905981, 2019). "Some circRNAs, such as circRNA-ITCH and hsa_circ_0043256, reportedly play a protective role in lung cancer by up-regulating its parental gene ITCH expression and inactivating the Wnt/β-catenin pathway." (PMID 30611252, 2019). "CircRNA ITCH inhibited the activation of Wnt/β-Catenin signaling pathway in lung cancer cells by down-regulating ITCH, thus restraining cancer cell proliferation." (PMID 29891014, 2018). "Similar to lung cancer, downregulation of circ-ITCH is also observed in 684 ESCC tissues and para-carcinoma tissues." (PMID 30064463, 2018). "Cir-ITCH, which acts as tumor suppressor gene in lung cancer and CRC has also generally been shown to be down-regulated in ESCC, following the analysis of 684 ESCC and their adjacent noncancerous tissues." (PMID 28969099, 2017). "The results showed that the expression of cir-ITCH was significantly decreased in approximately 73% of the lung cancer tissues." (PMID 28969099, 2017). "In our study, we found that miR-7, miR-214, and miR-128 (data not shown) decreased ITCH expression by binding to its 3′-UTR in lung cancer cell lines, and cir-ITCH acts as a sponge for miR-7 and miR-214, except miR-128." (PMID 27642589, 2016). "Ectopic expression of cir-ITCH markedly elevated its parental cancer-suppressive gene, ITCH, expression and inhibited proliferation of lung cancer cells." (PMID 27642589, 2016). "To study the correlation between cir-ITCH and ITCH in lung cancer, we assessed the expression of cir-ITCH in randomly selected 20 pairs of tissue samples from the 78 patients." (PMID 27642589, 2016). "The results showed that the expression of cir-ITCH was significantly decreased in lung cancer tissues." (PMID 27642589, 2016). "As parental gene of cir-ITCH, ITCH also decreased in lung cancer patients and positively correlated with cir-ITCH." (PMID 27642589, 2016). "In lung cancer cells, we found that miR-7 and miR214 promoted cell proliferation; this activity was totally abrogated with ectopic cir-ITCH hyperexpression." (PMID 27642589, 2016). "The results showed that patients with higher cir-ITCH expression levels in lung cancer tissues had a substantial upregulation of linear ITCH (R2 = 0.33, p < 0.01)." (PMID 27642589, 2016). "To further study the role of cir-ITCH in lung cancer progression, we constructed a recombinant vector to express cir-ITCH in lung cancer cell lines according to the previous studies." (PMID 27642589, 2016).
lung carcinoma (continued). "The MR‐1/ITCH/NICD3/HES1 axis may be a promising therapeutic target in the progression of lung cancer." (PMID 38342606, 2024). "In summary, the interruption of MR‐1/ITCH/ NICD3/HES1 axis may be a new strategy for lung cancer treatment." (PMID 38342606, 2024). "ITCH indirectly inhibits the Wnt/β-catenin signaling pathway, whose aberrant activation is crucial for the initiation, progression, and metastasis of lung cancer." (PMID 37762133, 2023). "Therefore, increased expression of ITCH, which is normally underexpressed in lung cancer, regulates cell proliferation by blocking the Wnt/β-catenin pathway." (PMID 37762133, 2023). "Similarly, circ-ITCH is shown to sponge miR-7 and miR-214 resulting in inhibition of lung cancer via increased expression of the ITCH gene." (PMID 34488780, 2021). "The circRNA of hsa_circRNA_001141 in lung cancer tissues has been shown to suppress the development of lung cancer by enhancing the expression of its parental gene ITCH, while hsa_circ_0013958 in lung cancer cells can promote the proliferation of lung cancer cells and inhibit apoptosis." (PMID 34329377, 2021). "Moreover, circITCH competitively inhibited miR-7 binding to ITCH remarkably enhances the expression of ITCH which promotes the oncogenesis of lung cancer by activating Wnt/β-catenin signal pathway." (PMID 32467668, 2020). "For instance, significant down-regulation of circRNA ITCH was discovered in lung cancer and up-regulating its expression could markedly elevate its parental cancer-suppressive gene ITCH through sponging oncogenic miR-7 and miR-214." (PMID 29891014, 2018). "Similar to lung cancer, circ-ITCH is also significantly downregulated in CRC tissues." (PMID 30064463, 2018). "The results of mechanism studies showed that ectopic expression of cir-ITCH could facilitate ITCH expression via sponging miR-214 or miR-7, further leading to the inhibition lung cancer cell proliferation." (PMID 29416705, 2018). "To further confirm whether cir-ITCH regulates the Wnt/β-catenin signaling pathway in lung cancer cells, we used a β-catenin/T-cell factor- (TCF-) responsive luciferase reporter assay." (PMID 27642589, 2016). "In conclusion, our study demonstrates that the cir-ITCH acts as a sponge for miR-7 and miR-214, promotes the expression of their target gene ITCH, and thus regulates lung cancer cell proliferation by indirectly inhibiting the activation of Wnt/β-catenin pathway." (PMID 27642589, 2016). "To address this hypothesis, we detected the expression of cir-ITCH in primary tumor tissues and different lung cancer cell lines." (PMID 27642589, 2016). "Altogether, our results suggested that cir-ITCH may play an inhibitory role in lung cancer progression by enhancing its parental gene, ITCH, expression." (PMID 27642589, 2016). "As that observed in colorectal cancer, cir-ITCH also plays a tumor suppressive role by regulating the activities of miR-7 and miR-214, which up-regulates the expression level of ITCH and inhibits the Wnt pathway, leading to reduced lung cancer cell proliferation." (PMID 29096676, 2017). "Therefore, cir-ITCH likely plays an inhibitory role in ESCC and colorectal and lung cancer, through promoting ITCH-mediated ubiquitination and subsequent proteasome-mediated degradation of phosphorylated Dvl2 scaffold protein, which impairs the canonical Wnt/β-catenin signaling." (PMID 29349062, 2017). "Thus, cir-ITCH can act as sponge of ITCH to interact with miR-7 and miR-214 in lung cancer cells." (PMID 27642589, 2016). "Hence, we speculated that ITCH may play a tumor suppressive role in lung cancer, and there is a possible connection between ITCH and cir-ITCH." (PMID 27642589, 2016). "However, the function of cir-ITCH in lung cancer is still unclear." (PMID 27642589, 2016). "Thus, in this study, we hypothesized that cir-ITCH might compete with ITCH to bind to miR-7 and miR-214 and may be involved in lung cancer development." (PMID 27642589, 2016).
lung carcinoma (continued). "In contrast to our findings, circ_0043256 has been reported as tumor-suppressive in lung cancer, acting through distinct axes (e.g., miR-1206/KLF2, miR-1252/ITCH, and multiple miRNA-mediated networks) to inhibit proliferation and growth." (PMID 41568058, 2026). "Despite these limitations, the findings from our research offer significant insights for the clinical application of ITCH E3 ligase, miR494 or STAT3 as potential targets in the future exploration of lung cancer." (PMID 39099000, 2024). "Previous studies revealed that circ-ITCH was down-regulated in ESCC, colorectal cancer and lung cancer and inhibited these tumors progression." (PMID 29386015, 2018). "Knockout of DUSP14, and that of ITCH or CYLD promotes progression of EAE and lung cancer, respectively, accompanied with sustained activation of TAK1 signaling." (PMID 28106845, 2017). "Cir-ITCH expression was downregulated in ESCC, colorectal, and lung cancer tissues, when compared to adjacent peritumoral tissues." (PMID 29349062, 2017). "For example, cir-ITCH could act as sponge of miRNAs to enhance ITCH expression and thus suppress the activation of Wnt/β-catenin signaling in ESCC, lung cancer and colorectal cancer." (PMID 28410211, 2017). "Correlation analysis showed that cir-ITCH expression in lung cancer tissues was not correlated with clinicopathological characteristics except age." (PMID 27642589, 2016).